ATM (ATM serine/threonine kinase)
Diseases named in the same sentence as ATM in open-access papers (continued):
Sharing a sentence is not in itself a finding about the gene and the disease.
breast cancer (continued). "The results of these studies are inconclusive, with some studies reporting an increased breast cancer risk and others failing to demonstrate such an effect in heterozygote ATM mutation carriers." (PMID 16622469, 2006). "The attribution of ATM candidacy as a breast cancer susceptibility gene stems from two sources." (PMID 16622469, 2006). "A number of studies have searched for germ line ATM mutations in breast cancer cases and/or compared the frequency of common variants among breast cancer cases to population controls, but the evidence regarding the role of ATM as a breast cancer susceptibility gene has been contradictory." (PMID 16914028, 2006). "Thus, controversy remains both regarding which type of mutations in the ATM gene are involved in breast cancer aetiology and which mutations actually drive the association with the risk of breast cancer." (PMID 17132159, 2006). "With calculated mutation carrier frequencies in the general population in the order of 0.5–1% for ATM gene mutations, ATM heterozygosity might be responsible for a sizeable proportion of breast cancers in the (female) population." (PMID 15942625, 2005). "A large proportion of the members of AT families are carriers of AT-causing gene mutations in ATM (Ataxia Telangiectasia Mutated), and it has been hypothesised that these otherwise healthy carriers are predisposed to breast cancer." (PMID 15942625, 2005). "This strategy may reduce breast cancer mortality by ~ 60% for women with ATM pathogenic variants." (PMID 40974429, 2025). "With these associations, the designation of ATM as BRCA3 (Breast Cancer 3) could be suggested; in fact, greater information and clinical management guidelines are already included in the National Comprehensive Cancer Network® (NCCN) guidelines for mutations in this gene." (PMID 40259910, 2025). "ATM mutations are more difficult to interpret than mutations in other breast cancer susceptibility genes because the risk of cancer may vary by mutation and many of the high penetrance mutations are missense mutations, which are difficult to distinguish from benign polymorphisms." (PMID 39543654, 2024). "This study evaluated the effect of age at breast cancer diagnosis and cancer family history on the risk of carrying a PV in breast cancer susceptibility genes routinely included in breast cancer predisposition multi-gene panels, ATM, BRCA1, BRCA2, CHEK2, and PALB2." (PMID 37084156, 2023). "Furthermore, we analyzed the breast cancer predisposition genes in each molecular subtype, resulting in the characterization of ATM (OR, 2.91; 95% CI, 1.25–6.45) and PTEN (OR, 10.04; 95% CI, 1.44–111.08) as predisposition genes exclusively in the HR+/HER2– subtype." (PMID 38114467, 2023). "In fact, it has been shown that the risk and aggressiveness of breast cancer oncogenesis do vary with ATM penetrance and expressivity; yet to our knowledge, it remains unknown whether this concept extends to radiosensitization phenotype and late treatment effects." (PMID 37206490, 2023). "In addition, AT patients have an increased risk of developing malignant tumors, and are prone to lymphoma, leukemia, etc., and their relatives who carry heterozygous mutations in the ATM gene are also prone to various tumors, such as breast cancer and gastric cancer." (PMID 35586824, 2022). "When ATM is mutated, it may increase the risk for developing breast cancer." (PMID 35563397, 2022). "Metformin was also reported as an adjuvant that could increase the complete pathological response rate of HER2-positive breast cancer patients bearing the rs11212617 single-nucleotide polymorphism (SNP) located near the ataxia telangiectasia mutated (ATM) gene." (PMID 36013384, 2022).
breast cancer (continued). "Furthermore, in a few rare cases, it could lead to an important rebound for the parents’ health itself, as with the mother of case 4 in that being a heterozygous carrier of an ATM mutation has to undergo stricter breast cancer screening." (PMID 35886058, 2022). "Mutations in the ATM gene caused Ataxia Telangiectasia (A-T), an autosomal recessive syndrome that patients have symptoms such as ionizing radiation sensitivity, cerebellar neurodegeneration immunodeficiency and markedly increased risk of cancers like breast cancer." (PMID 33402103, 2021). "Therefore, this variant was not marked as incidental finding, as would be the case for an heterozygous ATM variant that might increase the risk of breast cancer." (PMID 34992599, 2021). "Furthermore, the ATM mutations account for more than 7% of breast cancer patients." (PMID 33662042, 2021). "Up to 2% of the whole human population is heterozygous for a pathogenic ATM variant and it has been demonstrated that healthy carriers, such as the parents of A-T patients, are more susceptible to tumor formation, with a 5- to 9-fold increased risk of breast cancer in women." (PMID 32127026, 2020). "Therefore, it will be important to evaluate if a similar approach could be employed to personalise therapy in ATM-deficient MYC overexpressed breast cancers." (PMID 30746633, 2019). "However, many studies and a large meta‐analysis agree that ATM mutations confer a moderate breast cancer risk 36, 38, 39 although there might be differences between truncating versus missense mutations." (PMID 29271107, 2018). "We identified that ATM-associated DNA damage is responsible for SALL1-mediated breast cancer cell senescence, by analyzing activation of ATM and its related targets, as well as using loss-of-function approaches with a specific pharmacological ATM inhibitor and shRNA." (PMID 29625565, 2018). "Consistent with this hypothesis, we found that ATM-deficient cancer lines are more sensitive to CC-115 than ATM proficient lines, suggesting patients with ATM-deficient tumors such as breast cancer as potential patient populations for clinical development of CC-115." (PMID 29088817, 2017). "Nguyen etc used two exons of ATM, both containing an SNP interfering with standard mutation scanning to screen 1356 subjects from an international breast cancer genetics Study IInd improved identification of rare known and unknown variants, while dramatically reducing the sequencing effort." (PMID 27557076, 2016). "In addition, we also identified a sporadic breast cancer patient carrying a nonsense mutation, with loss of the wild-type allele, which could be a biologically significant ATM mutation." (PMID 25625042, 2015). "However, the pattern of ATM mutations and their role in breast cancer etiology has been controversial and remains unclear." (PMID 25625042, 2015). "Genetic factors play an important role in breast cancer (BC) development, including the presence of BRCA1, BRCA2, ATM, and other genes, but only 5% of BC incidence can be explained by mutation in these high-penetrance genes." (PMID 25636233, 2015). "In addition, low levels of ATM protein expression have been associated with severe adverse normal tissue reaction in breast cancer patients, suggesting that ATM protein levels may represent an independent predictive biomarker for clinical radiosensitivity." (PMID 25625042, 2015). "As ATM mutations and loss of ATM expression can be found in hereditary and sporadic breast cancers and A-T heterozygotes can be diagnosed, we hypothesized that such data might be useful in extending the molecular predictors required for selecting patients responsive to PARP inhibition." (PMID 24252502, 2013). "Therefore, the increased expression of oncomirs and the repression of some tumor suppressor miRNAs in ATM-deficient cells suggest that it may be possible to develop biomarkers for breast cancer predisposition." (PMID 23741392, 2013).
breast cancer (continued). "Additionally, it has been implicated that epigenetic silencing of ATM through methylation may also play a role in breast cancer susceptibility." (PMID 23741392, 2013). "However, these ATM mutation carriers may merit different approaches to treatment for breast cancer due to their increased radiosensitivity or efficacy of specific chemotherapies associated with ATM mutations." (PMID 23586058, 2013). "The rationale was that rare alleles at HRAS, which are associated with a two-fold increase in the risk of breast cancer as well as with an increased propensity for double-strand breaks, may interact with high-risk alleles at ATM, which participates in DNA double-strand break repair." (PMID 21187953, 2010). "Carriers of mutations predicted to encode a full-length ATM protein had cancer risks similar to those of people carrying truncating mutations, predicting that both type of mutation in these families are pathogenic for ataxia-telangiectasia as well as for breast cancer." (PMID 17428320, 2007). "We examined the prevalence of two ATM gene mutations among women with unilateral and bilateral breast cancer; one out of 638 unilateral cases carried the 7271T>G mutation, while one out of 511 bilateral and eight out of 638 unilateral breast cancer cases harboured the IVS10-6T>G mutation." (PMID 14562025, 2003). "This suggests potential for improving treatment outcomes in solid breast cancer, especially in patients with defects in DNA repair pathways like BRCA or ATM mutations." (PMID 41557625, 2026). "ETO (20 μM) concentration for 2 hour was able to induce the phosphorylation and activation of p-ATM kinase in breast cancer cells suggesting that the DNA repair is initiated in the cells after ETO treatment and is still functional in the breast cancer cells." (PMID 41557625, 2026). "Beyond the high-penetrance genes associated with breast cancer, moderate-risk genes, such as ATM, BARD1, and CHEK2, also contribute to hereditary breast cancer predisposition and are therefore considered part of the HBOC spectrum." (PMID 41528496, 2026). "The 5-year cumulative risk (CR) of contralateral breast cancer (CBC) was 0.55 for BRCA1/2, 0.89 for ATM, and 0.80 for CHEK2 carriers." (PMID 41976331, 2026). "For example, mutations in BRCA1/2, ATM and PALB2 are most associated with breast cancer; mutations in ATM and BRCA2 are commonly associated with prostate cancer; mutations in BRCA1/2 are commonly associated with ovarian cancer." (PMID 40192976, 2025). "The risk associated with breast cancer for P/LP variants in PALB2 varied between moderate and high (OR 3.83–5.02), whereas those in CHEK2 and ATM were associated with moderate risk (OR 2.54–2.47 and OR 1.82–2.10, respectively)." (PMID 39858629, 2025). "Major radiosensitizers relevant for breast cancer also include mTOR inhibitors, ATM inhibitors and PLK-4 inhibitors." (PMID 40667051, 2025). "HRD-positive luminal breast cancers with ATM or BRCA1/BRCA2 defects show tumor reduction with PARPi." (PMID 40864792, 2025). "Specific genetic alterations, such as mutations in DNA repair genes (BRCA1 (Breast Cancer 1), BRCA2 (Breast Cancer 2), ATM (Ataxia-Telangiectasia Mutated)), predict treatment outcomes and guide therapy-related decisions." (PMID 40862806, 2025). "For ATM c.7570G > C carriers, the family history was less striking, as 5/13 (38%) of the carriers had 1st or 2nd degree relatives with breast cancer, despite the high OR estimate." (PMID 40009290, 2025). "Protein-truncating variants in established susceptibility genes BRCA2, BRCA1, CHEK2, PALB2, ATM and MAP3K1 were associated with a risk of breast cancer, while BARD1 and ATRIP met exome-wide significance for the first time." (PMID 41044259, 2025). "The GEN1 gene is implicated in DNA damage repair, as are several high- or moderate-risk breast cancer susceptibility genes, i.e., BRCA1, BRCA2, PALB2, CHEK2, ATM, and BRIP1." (PMID 40649769, 2025).
breast cancer (continued). "First, GNPDA1 was strongly associated with “DNA damage_ATM activation by DNA damage (p = 4.282 × 10−06)”, “BRCA1 and BRCA2 in breast cancer (p = 6.950 × 10−04)”, and “DNA damage_ATM/ATR regulation of G2/M checkpoint: nuclear signaling (p = 8.093 × 10−04)”." (PMID 40278313, 2025). "A similar calculation for breast cancer was conducted by using BRCA1/2 as high-risk genes and CHEK2, ATM and PALB2 for intermediary risk genes." (PMID 40016794, 2025). "We characterized breast cancer risk associated with established risk factors among WHI participants who carry PVs in BRCA1/2, ATM, CHEK2, and PALB2." (PMID 40298171, 2025). "We report on penetrance and breast cancer risk–modifying factors for PVs in BRCA1/2, ATM, CHEK2, and PALB2 among WHI participants." (PMID 40298171, 2025). "A notable strength of this study is its gene-specific analysis, identifying mutations in ATM (OR = 3.97) and DNMT3A (OR = 1.33) as key contributors to breast cancer risk." (PMID 41382403, 2025). "HOTAIR over expression in invasive ductal carcinoma leads to increased expression of DNA repair factors like KU70, KU80, DNA-PK and ATM regulating breast cancer cell proliferation by regulating apoptosis and the cell cycle." (PMID 39940704, 2025). "Eight different genes, including ATM, BRCA1, BRCA2, CHEK2, PALB2 (FANCN), RAD51C, and RAD51D, demonstrate significant correlations with an increased risk of breast cancer when harboring pathogenic variations." (PMID 40800071, 2025). "Most breast cancer susceptibility genes are involved in the damage repair signaling pathway, i.e., including BRCA1, BRCA2, PALB2, CHEK2, ATM, BARD1, RAD51C, and RAD51D." (PMID 40649769, 2025). "The results showed an association between the 86-SNV PRS and breast cancer risk for each of the carrier populations: BRCA1 (OR 1.20; 95% CI 1.10–1.32), BRCA2 (OR 1.23; 95% CI 1.12–1.34), ATM (OR 1.37; 95% CI 1.21–1.55), and PALB2 (OR 1.34; 95% CI 1.16–1.55)." (PMID 39858629, 2025). "It has been reported that patients with pancreatic cancer carry rare germline deleterious variants of breast cancer susceptibility genes such as BRCA1, BRCA2, PALB2, and ATM." (PMID 38204267, 2025). "This is in parallel with variants in genes implicated in hereditary breast cancer including the ‘high risk’ genes BRCA1, BRCA2, and PALB2 and ‘moderate risk’ genes CHEK2 and ATM." (PMID 41327266, 2025). "Multiple other players from the DDR pathway, including PALB2, ATM, and CHEK2, are also connected to breast cancer predisposition, although with lower risk." (PMID 40009290, 2025). "Conversely, BRCA2, ATM, PALB2, and CHEK2 were more commonly associated with later-onset breast cancer, for which the penetrance estimates ranged from 19% to 31% by age 60 years." (PMID 39858629, 2025). "They reported that miR-181a and miR-181b overexpression in more aggressive breast cancers correlates inversely with ATM levels." (PMID 41065894, 2025). "For example, in the human breast carcinoma cell line ZR-75-1, A-to-I editing of ATM and POLH transcripts is enhanced, accompanied by elevated expression levels of these genes, as shown by RNA-seq analysis." (PMID 41164819, 2025).
breast cancer (continued). "Also, there are particular P/LP variants in moderate penetration genes that confer similar risks of BC as high-risk genes, for instance, the missense pathogenic variant c.7271T>G in ATM may considerably increase the risk of breast cancer in a similar proportion as P/LP variants in BRCA2." (PMID 40508121, 2025). "We found that breast cancer susceptibility variants in BRCA1, BRCA2, ATM, and CHEK2 were associated with development of CBC in a subtype-specific manner." (PMID 39786405, 2024). "As well, some chemotherapeutic agents are reported to upregulate CD155 expression through ATM/ATR-related kinases in breast cancer, probably enhancing its poor prognostic role." (PMID 39267111, 2024). "In patients with breast cancer, a high incidence of pathogenic variants of BRCA1 and BRCA2 is observed, as well as other highly mutated genes, such as PALB2, CHEK2, MUTYH, and ATM." (PMID 39335183, 2024). "Prospective studies follow unaffected ATM carriers forward in time to estimate the incidence of breast cancer in ATM carriers." (PMID 39543654, 2024). "Our results from all-comers population genetic screening confirmed that rare pLOF variants in BRCA1, BRCA2, PALB2, ATM, and CHEK2 confer significant risk to breast cancer in the overall population." (PMID 39669587, 2024). "Deleterious germline variants in ATM and CHEK2 have been associated with a moderately increased risk of breast cancer." (PMID 39209703, 2024). "Recent comprehensive studies have highlighted that pathogenic variants (PVs) across eight distinct genes, such as ATM, BRCA1, BRCA2, CHEK2, PALB2 (FANCN), RAD51C, and RAD51D, exhibit a substantial correlation with breast cancer risk." (PMID 38397209, 2024). "The PVs in high-risk (BRCA1, BRCA2, PALB2) or moderate-risk (ATM, CHEK2) genes mainly associated with breast cancer in women follow an autosomal dominant inheritance pattern." (PMID 38722431, 2024). "Variants involving ATM, CHEK2, BRIP1, RAD51C, RAD51D, NBN and BARD1 are known to be associated with a moderately increased risk of breast cancer and a lifetime risk of around 25%." (PMID 38439815, 2024). "Several studies have demonstrated that ATM and PALB2 mutations confer a moderate risk of developing breast cancer." (PMID 39640102, 2024). "There are also multiple DNA repair genes that interact with the BRCA genes such as ATM, CHEK2, and BRIP1 that further increase the risk of breast cancer when mutated." (PMID 38927753, 2024). "Accordingly, combinatorial treatment with ATR inhibitors showed synergy with BUB1 inhibition in breast cancer cell lines with functional ATM activity." (PMID 38396175, 2024). "CPM decisions are also frequently observed in patients with ATM, CHEK2, and PALB2, which are the three most common moderate-risk breast cancer genes." (PMID 39335183, 2024). "While BRCA1 and BRCA2 remain the most well-known high-penetrance genes, others, such as ATM, BARD1, CHEK2, PALB2, RAD51C, and RAD51D, are now recognized as conferring moderate to high risk for breast cancer." (PMID 39590369, 2024). "In the absence of BRCA1/2 germline mutations, alterations in other specific homologous recombination (HR) genes, such as PALB2, CHEK2, ATM, and NBN, can lead to an increased risk of breast cancer development." (PMID 39272660, 2024).